YAP1 (Yes1 associated transcriptional regulator)
Diseases named in the same sentence as YAP1 in open-access papers (continued):
Sharing a sentence is not in itself a finding about the gene and the disease.
chordoma (4 papers, 2022 to 2025). Chordomas are rare malignant tumors arising from embryonic remnants of the notochord in axial skeleton. "CircTEAD1 regulates the Hippo signalling pathway by promoting the expression of Yap1 mRNA, thereby fuelling the aggressive nature of chordoma cells." (PMID 38659080, 2024). "The relationship between the Hippo pathway and circTEAD1 was further investigated by establishing animal models using chordoma cells stably transfected with empty vector, shCtrl, sh‐circTEAD1 or oe‐Yap1." (PMID 38659080, 2024). "Collectively, these findings establish the pivotal function of Yap1 in driving proliferation and invasion in chordoma." (PMID 38659080, 2024). "The findings offer novel insights into the potential molecular targets for chordoma therapy, shedding light on the intricate interplay between circRNAs, m6A modification and Yap1 mRNA in chordoma pathogenesis." (PMID 38659080, 2024). "The circTEAD1/IGF2BP3/Yap1 mRNA RNA‐protein ternary complex not only bolstered the stability of Yap1 mRNA but also exerted a pivotal role in driving chordoma tumorigenesis." (PMID 38659080, 2024). "Further assessments through colony formation and CCK‐8 assays unveiled the significant promotion of chordoma cell proliferation by Yap1." (PMID 38659080, 2024). "Afterwards, the same methods were utilized for the validation of the function of Yap1 in chordoma in vitro." (PMID 38659080, 2024). "Furthermore, m6A-modified circTEAD1 stabilizes YAP1 mRNA, which contributes to the tumorigenesis in chordoma." (PMID 40822927, 2025). "Moreover, these outcomes elucidate that circTEAD1‐dependent modulation of Yap1 is pivotal for tumorigenesis, suggesting a potential therapeutic target for chordoma management." (PMID 38659080, 2024). "This study aimed to investigate whether a regulatory relationship exists between circRNAs and Yap1 in the context of chordoma, leading to the identification of circTEAD1." (PMID 38659080, 2024). "Finally, the regulatory relationship between circTEAD1 and Yap1 in chordoma was verified by an in vivo tumour formation assay." (PMID 38659080, 2024). "In addition, the impact of Yap1 mRNA on the proliferative and invasive capacities of chordoma was demonstrated." (PMID 38659080, 2024). "Selinexor treatment may have led to a decrease in expression of Brachyury (n=4, p=0.037), a key driver of chordoma, as well as its downstream target YAP1." (PMID 36059685, 2022). "However, contrary to the proposed mechanism, it was demonstrated that circTEAD1 could form a circTEAD1/IGF2BP3/Yap1 mRNA ternary complex in the cytoplasm to regulate chordoma proliferation and invasion through the Hippo signalling pathway." (PMID 38659080, 2024). "Furthermore, elevated circTEAD1 expression enhanced Yap1 mRNA stability by forming a circTEAD1/IGF2BP3/Yap1 ternary complex, which led to chordoma invasion and proliferation." (PMID 38659080, 2024).
chronic pancreatitis (4 papers, 2019 to 2025). A chronic inflammatory process causing damage and fibrosis of the pancreatic parenchyma. "YAP1 has been shown to induce the activity of PSCs and stimulate pancreatic fibrosis during chronic pancreatitis." (PMID 36835366, 2023). "But the number of metaplastic ducts with YAP1 expression was elevated during the development of PDAC (from chronic pancreatitis/PanINs to PDAC)." (PMID 36180487, 2022). "Recent publications have demonstrated that miR-15a, which targets YAP1 and BCL-2, is significantly downregulated in patients with chronic pancreatitis compared to healthy controls." (PMID 36835366, 2023). "To investigate the role of miR-15a in chronic pancreatitis, we first assessed miR-15a levels and its targets (YAP1 and BCL-2) upon the development of chronic pancreatitis in Ptf1aCreERTM and Ptf1aCreERTM;LSL-KRASG12D mice." (PMID 36835366, 2023). "We demonstrated increased levels of YAP1 and BCL-2 (both targets of miR-15a) in pancreatic tissues obtained from Ptf1aCreERTM and Ptf1aCreERTM;LSL-KrasG12D mice after chronic pancreatitis induction as compared to controls." (PMID 36835366, 2023). "Interestingly, compared with PBS-treated controls, the increase in Yap1 in the pancreas revealed a 6-fold and 14-fold upregulation in Ptf1aCreERTM change in Ptf1aCreERTM;LSL-KRASG12D mice under chronic pancreatitis conditions, respectively." (PMID 36835366, 2023). "However, YAP1 staining intensity was not elevated from chronic pancreatitis/PanINs to PDAC." (PMID 36180487, 2022).
cognitive deficits (4 papers, 2022 to 2025). "In AD, preliminary evidence has shown FGF2 improved cognition by modulating ferroptosis and supporting neuronal survival, whereas YAP1 mitigates cognitive deficits and reverses AD pathology via CDK6 signaling or artemisinin activation." (PMID 40933191, 2025). "Our research indicates that inhibition of YAP1 in mice leads to accelerated neuronal senescence and cognitive impairment." (PMID 40468463, 2025). "Nevertheless, the precise regulatory mechanisms governing YAP1 expression and its biological properties in mediating the progression of cognitive impairment warrant further investigation." (PMID 40933191, 2025). "Drawing on these lines of evidence, we hypothesize that YAP1 may act as a compensatory neuroprotective factor generated during the onset of cognitive impairment." (PMID 40933191, 2025). "In the study of cognitive improvement by dexmedetomidine (Dex) in AD patients, the miR-129/YAP1/JAG1 axis may be a potential mechanism by which Dex protects against cognitive impairment in AD patients." (PMID 38516314, 2024).
cutaneous squamous cell carcinoma (4 papers, 2019 to 2023). "For instance, LINC01048 increases the binding of TAF15 to YAP1 promoter and gives rise to sustaining activation of Hippo pathway and hence promotes cell proliferation in cutaneous squamous cell carcinoma." (PMID 37257820, 2023). "LINC01048 is another tumor promoter that enhances proliferation while inhibiting apoptosis in cutaneous squamous cell carcinoma cells by increasing YAP1 expression." (PMID 35701841, 2022). "Further investigation revealed that LINC01048 recruits TAF15 (a transcriptional activator) to the YAP1 promoter to transcriptionally activate YAP1 in cutaneous squamous cell carcinoma cells." (PMID 35701841, 2022). "The up-regulation of LINC01048 induced by USF1 promotes cell proliferation and apoptosis in cutaneous squamous cell carcinoma by binding to TAF15 to activate YAP1 transcription." (PMID 32776110, 2020).
diabetic kidney disease (4 papers, 2024 to 2025). Progressive kidney disorder caused by vascular damage to the glomerular capillaries, in patients with diabetes mellitus. "The downregulation of miR-485-5p and upregulation of YAP1 were also identified in the serum of patients with diabetic nephropathy." (PMID 41020857, 2025). "Quercetin also inhibits HG-induced human mesangial cell proliferation, inflammation, and oxidative stress via the miR-485-5p/YAP1 axis, and therefore, this may provide a novel therapeutic target for diabetic nephropathy." (PMID 41020857, 2025).
diabetic retinopathy (4 papers, 2021 to 2025). "When Yap1 is knocked down, the proliferation, migration, and angiogenesis of retinal microvascular endothelial cells in mice with diabetic retinopathy are reduced." (PMID 36035997, 2022). "High levels of Yap1 expressed in the retinas of mice with diabetic retinopathy upregulate MALAT1 and target VEGFA by regulating miR-200b-3p." (PMID 36035997, 2022). "A recent study found that the upregulation of YAP1 plays a critical role in promoting angiogenesis during the development of diabetic retinopathy." (PMID 34370714, 2021).
fibrosarcoma (4 papers, 2018 to 2022). A malignant mesenchymal fibroblastic neoplasm affecting the soft tissue and bone. "We hypothesized that SAHA/JQ1 might reactivate clock gene expression owing to loss of YAP1 and observed upregulation of clock genes and proteins in treated mouse and human UPS cells, and HT-1080 human fibrosarcoma cells." (PMID 30382078, 2018).
heart failure (4 papers, 2020 to 2025). Inability of the heart to pump blood at an adequate rate to meet tissue metabolic requirements. "Postnatal upregulation of YAP1 retain CM proliferative capacity after birth causing cardiomegaly and heart failure." (PMID 36862248, 2023). "In later periods, persistent activation of YAP1 produces cardiac dysfunction and heart failure, which may be partly caused by the YAP1/TEAD1–OSM positive feedback loop and cardiac remodeling." (PMID 32390875, 2020). "Cardiac-specific deletion of YAP1 results in failure to adapt to pressure overload, which in turn accelerates heart failure transition with massive fibrosis." (PMID 36015285, 2022). "As mentioned in Section “Role of Hippo–YAP1/TAZ Signaling and Its Differentiation Output in Heart Development,” YAP1/TEAD1-OSM feedback cycle exacerbates heart failure and the progression of diabetic cardiomyopathy in HFD-fed mice following TAC." (PMID 32390875, 2020). "Consequently, cardiac-specific inhibition of NEDD8 attenuates the activity of CRLs and thereafter blunts the cell-proliferation activity of YAP1; this causes ventricular hypoplasia and non-compaction and, eventually, heart failure and neonatal death in mice." (PMID 32390875, 2020). "This positive feedback mechanism results in sustained YAP1 activation and redundant OSM, which exacerbates cardiac injury and heart failure upon PO." (PMID 32390875, 2020).
Hypertension (4 papers, 2024 to 2025). The presence of chronic increased pressure in the systemic arterial system. "Recently, irbesartan, an angiotensin type 1 receptor antagonist used for treating hypertension, was shown to overcome Gem resistance in PDAC models by suppressing stemness and iron metabolism via inhibition of the Hippo/YAP1/c-Jun axis." (PMID 40272619, 2025).
inflammatory bowel disease (4 papers, 2023 to 2025). A spectrum of small and large bowel inflammatory diseases of unknown etiology. "In models of inflammatory bowel disease, the up-regulation of gp130 signalling mediated by elevated levels of tumor IL-6 and IL-11 leads to Yap1 activation as a mechanism of wound healing." (PMID 37957015, 2024). "Telomere dysfunction‐induced activation of the ATM/YAP1/pro‐IL‐18 pathway may contribute to inflammatory bowel disease progression." (PMID 40066231, 2025). "Since YAP1 has been reported to regulate M1/M2 macrophage polarization in inflammatory bowel disease, we then examined whether YAP1 could regulate synovial inflammation by orchestrating macrophage polarization using a co‐culture system." (PMID 38044289, 2024).
intervertebral disc degeneration (4 papers, 2019 to 2025). "The activation of Yap1, which is a transcriptional coactivator as well as a negative regulator of the Hippo pathway, and is involved in intervertebral disc degeneration, was mainly affected in nucleus pulposus cells from Chsy3-deficient mice." (PMID 34901009, 2021). "However, the role of YAP1 in intervertebral disc degeneration (IDD) remains elusive." (PMID 30511395, 2019).
intestinal tumor (4 papers, 2015 to 2024). "Hence, the effect of actin polymerization on YAP1 was explored by using a mouse intestinal tumor-derived cell line MC38 and organoids." (PMID 37849945, 2023). "The fact that RASSF1A cooperates with APC loss to promote intestinal tumors suggests that SRC activation may contribute to colorectal tumorigenesis by promoting the tyrosine phosphorylations of both β-catenin and YAP1 that are required for nuclear localization and transcriptional activation." (PMID 26549256, 2015). "YAP1/TAZ is required for the formation and growth of intestinal tumors." (PMID 36479120, 2022).
Myocardial fibrosis (4 papers, 2020 to 2025). "In the transgenic heart, MST1 overexpression was shown to enhance the phosphorylation of YAP1 Ser127 and induce inactivation of YAP1; this induced cardiomyocyte (CM) apoptosis and myocardial fibrosis." (PMID 32390875, 2020). "Knockin mice expressing a nonphosphorylatable T226A YAP1 mutant display decreased ferroptosis, reduced myocardial fibrosis and improved heart function." (PMID 40279648, 2025).
ovarian tumors (4 papers, 2016 to 2024). "In the current study, our results reveal that the amplification of YAP1/TAZ and its expression are associated with high-grade serous subtype-specific ovarian tumor carcinogenesis." (PMID 38730733, 2024). "Noticeably, depletion of Cxcr1/2 receptors impeded the oncogenic effects of GROα, preventing intraperitoneal dissemination of ovarian tumors and highlighted the possibility of targeting the miR-141/YAP1/GROα/CXCR1/2 signaling cascade to combat OvCa metastases." (PMID 36624516, 2023). "Activation of YAP1 in ovarian tumors is negatively correlated with clinical outcomes and response to taxanes." (PMID 27036018, 2016). "Curiously, while YAP1 is associated with the Hippo pathway, the mRNAs that were strongly inversely correlated to miR-509-3p in TCGA ovarian tumors were enriched not for Hippo pathway genes but for structural and regulatory components of the ECM." (PMID 27036018, 2016). "The ROC curve results demonstrate that the Hippo gene set, YAP1, and MST1 genes could predict the serous subtype ovarian tumors with better specificity and sensitivity with significant areas under the curve (AUC) and p values (p < 0.05)." (PMID 38730733, 2024).
posterior fossa ependymoma (4 papers, 2023 to 2024). A high grade ependymoma that is located within the posterior fossa. "Ependymomas are classified into supratentorial ZFTA fusion-positive, supratentorial YAP1-fusion positive, posterior fossa ependymoma group A and posterior fossa ependymoma group B." (PMID 39361075, 2024).
prostate adenocarcinoma (4 papers, 2019 to 2022). "A smaller study compared the expression of YAP1 in 22 benign prostatic hyperplasia samples to increasing grades of prostate adenocarcinoma and 12 neuroendocrine biopsy samples." (PMID 33557087, 2021). "They found that YAP1 is localised to basal epithelial cells in normal prostate and its protein expression increased with grade in prostate adenocarcinoma." (PMID 33557087, 2021). "Further analysis of YAP1 mRNA data in Prostate Adenocarcinoma MSKCC dataset (n = 216) revealed that 51% of patients have decreased YAP1 mRNA levels." (PMID 31835563, 2019). "We analyzed mRNA expression of both NEK1 and YAP1 in prostate adenocarcinoma (PRAD) and head and neck squamous cell (HNSC) carcinoma patients from TCGA datasets using the UALCAN online platform." (PMID 33297404, 2020).
type 2 diabetes (4 papers, 2018 to 2025). "Gene association studies have so far identified 16 candidate loci involved in PCOS, including genes involved in gonadotropin action (LHCGR and FSHR), metabolism and sexual development (ESR1), insulin signaling and type 2 diabetes (INSR, THADA, HMGA2) or cell proliferation (YAP1 and SUMO1P1)." (PMID 40551954, 2025).
viral infection (4 papers, 2019 to 2025). "The overexpression of the yes-associated protein 1 (YAP1) oncogene in cervical epithelial cells can induce the downregulation of genes encoding ISGs that directly inhibit virus infection, such as MX1, ISG15, APOBEC3G, OAS1, TRIM5, and IFI44L." (PMID 34681093, 2021). "In addition, PINK1 interacts with Yes-associated protein 1 (YAP1) upon viral infection and impairs YAP1/IRF3 complex formation." (PMID 31139191, 2019). "Considering that PINK1 binds IRF3 after viral infection in macrophages, we speculate that YAP1 might be involved in the PINK1-mediated antiviral innate immune response." (PMID 31139191, 2019). "Recently, YAP1 was identified as a negative regulator of innate immunity by interacting with IRF3 to impair dimmer formation and nuclear translocation after viral infection." (PMID 31139191, 2019). "For example, YAP1 inhibits the production of type I IFN by interacting with IRF3, blocking its dimerization and nuclear translocation, thereby preventing IRF3-mediated type I IFN expression in response to viral infection." (PMID 40784457, 2025). "Our finding that HPV E7 activates YAP1 to manipulate cell fate opens up an exciting new line of inquiry into how YAP1, TAZ, and the Hippo signaling pathway could impact viral infections by regulating tissue developmental processes." (PMID 35170430, 2022).
cataract (3 papers, 2022 to 2025). Partial or complete opacity of the crystalline lens of one or both eyes that decreases visual acuity and eventually results in blindness. "The role of the ordered arrangement of LFCs has been demonstrated in several animal studies, and Yap1 heterozygous deletion mice exhibit cataracts." (PMID 40196848, 2025). "Recent studies have demonstrated that, in mice, one allelic deletion of Yap1 dramatically lowered LEC cell density, disrupted local cell adhesion and caused cataracts." (PMID 38613348, 2024).
cervical (3 papers, 2019 to 2025). "Our data clearly indicate that hyperactivation of YAP1 increased viral infectivity and suppressed innate immunity, two events that greatly increase the susceptibility of cervical epithelial cells to HPV infection and facilitate the establishment of persistent HPV infection in these cells." (PMID 30840887, 2019). "The Gene Expression Omnibus (GEO) datasets, were utilized to assess the expression profiles of TP63 and YAP1 in the cervical SCC and ADC samples by using the GEO2R tool." (PMID 40603978, 2025). "Hyperactivation of PI3K increases YAP1 activity in HCvECs, thereby inducing cervical tumorigenesis." (PMID 41256331, 2025). "Introduction of HPV16 E6 and E7 oncoproteins significantly promoted cervical carcinogenesis of KRT14-YAPS127A cells, indicating that synergetic function between YAP1 and HPV does exist during cervical tumorigenesis." (PMID 30840887, 2019).
chondrosarcoma (3 papers, 2022 to 2024). A malignant cartilaginous matrix-producing mesenchymal neoplasm arising from the bone and soft tissue. "Upon upregulation of p21, loss of YAP1 inhibited chondrosarcoma cell proliferation and induced senescence in chondrosarcoma cells." (PMID 35701841, 2022). "Recent studies have demonstrated that PRMT 1, a type I PRMT, functions as a positive regulator of YAP1 activity in chondrosarcoma, while PRMT5, a type II PRMT, promotes laryngeal cancer cell growth and its invasive capacity through the LATS2 and YAP1 signaling pathways." (PMID 38444414, 2024). "PRMT1 has been identified as a positive regulator of YAP1 activity in chondrosarcoma." (PMID 38444414, 2024).
cognitive decline (3 papers, 2021 to 2025). "By elevating YAP1 levels, we can effectively counteract both the aging process and cognitive decline associated with AD." (PMID 40468463, 2025). "Knockdown of YAP1 induced AD-like symptoms and exacerbated cognitive decline in 2-month-old C57BL/6J mice." (PMID 40468463, 2025). "Specifically, in the early stages of cognitive decline in MCI, the compensatory elevation of plasma YAP1 protein levels may represent a protective response mechanism against the progression of cognitive dysfunction." (PMID 40933191, 2025).